CXCL10 (C-X-C motif chemokine ligand 10)
Diseases named in the same sentence as CXCL10 in open-access papers (continued):
Sharing a sentence is not in itself a finding about the gene and the disease.
COVID-19 (continued). "Moreover, the levels of CXCL10 and IL-6 are more than 10 times higher in patients with severe course and mild–moderate COVID-19 in comparison to healthy volunteers." (PMID 35409036, 2022). "Therefore, more research on the antagonism of CXCL8, CCL2, CCL3, and CXCL10 in influenza and COVID-19 is required." (PMID 35674675, 2022). "Therefore, in this review paper, we focus on the role of CXCL10 overactivity in the pathogenesis of COVID-19." (PMID 35409036, 2022). "We found higher plasma levels of CXCL10 in COVID-19 patients compared to HDs." (PMID 36030261, 2022). "In a COVID-19 cohort, the depletion of several bacterial species (B. adolescentis, E. rectale and F. prausnitzii, known to play immunomodulatory roles in the human GI system) was linked to increased plasma concentrations of TNF-α, CXCL10, CCL2 and IL-10." (PMID 35956081, 2022). "Moreover, although CXCL10 and IL-6 were universally found with increased levels in all COVID-19 subgroups, the magnitude order was higher in MV and Death compared to nMV and Discharge." (PMID 36451835, 2022). "They revealed that plasma and epithelial lining fluid CXCL10 concentrations were increased in group of patients with ARDS caused by COVID-19 in comparison to non-COVID-19 groups of patients." (PMID 35409036, 2022). "In addition, a chemokine, CXCL10, is found relevant in the prediction of worse outcomes due to infection, since its expression pattern in COVID-19 patients differs from that seen in individuals with other types of viral infections." (PMID 35159388, 2022). "Modulation of CXCL10 activity seems to be a promising and effective therapeutic target of COVID-19." (PMID 35409036, 2022). "CCL3 and CXCL10 levels were higher in LTBI/COVID-19 vs. COVID-19." (PMID 36090983, 2022). "Indeed, CXCL10 concentration is higher in COVID-19 deceased patients, and it is directly correlated with the duration of mechanical ventilation in subjects with acute respiratory distress syndrome (ARDS) due to SARS-CoV-2 infections." (PMID 35844604, 2022). "Consequently, several studies reported CXCL10 as an excellent predictive biomarker of patient outcomes in COVID-19." (PMID 36366543, 2022). "Similarly, proinflammatory M1-like macrophages that express high levels of the chemokines CCL2, CCL3 and CXCL10 are abundant in BAL fluid from patients with severe COVID-19, suggesting a pathologic role for inflammatory lung macrophages in COVID-19 as well." (PMID 35271686, 2022). "From these, CXCL10, a downstream IFNy effector molecule, shows a strong correlation with disease severity (Yang and others 2020) and is highly detectable in the airways of COVID-19 patients (Reynolds and others 2021)." (PMID 35674675, 2022). "Accordingly, the effects of gender, age, DM, and HT on the salivary levels of IL-6, CRP, and CXCL-10 observed in SARS-CoV-2 patients might be consequences of their impacts on COVID-19 disease severity." (PMID 35967091, 2022). "So, it has been suggested that the chemokine CXCL10, through CXCR3, is associated with inflammatory diseases and may be involved in the development of COVID-19." (PMID 35409036, 2022). "The expression level of CXCL10 has shown a strongly significant positive correlation with viral load and progression of COVID-19, thus it could be also used as a biomarker for COVID-19 acute respiratory distress syndrome (ARDS) patients." (PMID 35922752, 2022). "CCL2, CXCL10, and CXCL8 are the most commonly found chemokines associated with COVID-19 severity." (PMID 35782361, 2022). "CXCL10 has been found in the BALF from patients with COVID-19 who had higher proinflammatory genes." (PMID 35464491, 2022). "The robustness of CXCL10 as a biomarker may outweigh its role as a surrogate marker of the COVID-19 cytokine storm width and amplitude." (PMID 34663207, 2021).
COVID-19 (continued). "Furthermore, in the peripheral blood mononuclear cells (PBMCs) isolated from the BALF of patients with COVID-19, overexpression of a set of genes encoding for several chemokines, including CCL2, CXCL10, CCL3, and CCL4, was recorded." (PMID 33946736, 2021). "CXCL-10, the most prominently elevated cytokine in COVID-19 patients in this study may be useful as an inflammatory marker related to COVID-19." (PMID 34242356, 2021). "Recently, it was observed in a study that in normal patients, there was a lower level of classical inflammatory cytokines like G-CSF, CCL-20, IL-1β, IL-2, IL-6, IL-15, TNF-α, and TGF-β while at the same time, there was a higher plasma level of GM-CSF and CXCL-10 in COVID-19 patients." (PMID 34305892, 2021). "IP-10 has been found to correlate significantly with the severity level of COVID-19 patients, with values only slightly increased in asymptomatic cases but highly elevated in moderate and critically ill patients—thus suggesting CXCL-10 as an independent predictor for COVID-19 progression." (PMID 33445810, 2021). "CXCL10: CXCL10 is a frequently studied gene in multiple COVID-19 genetic studies." (PMID 34109284, 2021). "•ACE2 and CXCL10 are found as the hub proteins in the PPI network of COVID-19 development." (PMID 33585826, 2021). "CXCL10 concentration abated in COVID-19 survivors after healing and discharge from the hospital." (PMID 34663207, 2021). "CXCL10 results from a data-driven analysis, that accounts for presence of confounding factors, as the most robust predictive biomarker of patient outcome in COVID-19." (PMID 34663207, 2021). "Altogether, our results suggest that decreased activation of pDCs, mDCs, and monocytes and the delayed and prolonged IFN-α secretion along with increased CXCL-10 secretion may be responsible for the increased morbidity and mortality of males to COVID-19." (PMID 34745109, 2021). "We identified several AD marker genes (e.g., NKTR, GSTM3, TGFB1, TNFRSF1B, SPP1, and CXCL10) which may provide insights into the shared pathobiology of cognitive dysfunction in COVID-19 and AD." (PMID 34108016, 2021). "Also, consistently up-regulated is CXCR3, the receptor for CXCL10, one of the soluble mediators most induced in severe COVID-19 blood." (PMID 34433692, 2021). "CCL2 and CXCL10 are chemokines, CCL2 facilitates the migration and infiltration of monocytes/macrophages to sites of inflammation produced by either tissue injury or infection, CXCL10 could drive longer duration of mechanical ventilation during COVID-19 ARDS." (PMID 34489974, 2021). "In hospitalised COVID-19 patients, DN2 cells are associated with high neutralising antibody titres and elevated plasma concentrations of inflammatory biomarkers, such as CRP, CXCL10, and IL-6." (PMID 34964023, 2021). "This inflammatory transcriptional signature, as shown by RNA Seq and confirmed by qPCR for Il-6, type I IFN (Ifn-β) and Cxcl10 is consistent with the recent neuropathological description of deceased patients with COVID-19, where microgliosis was seen in the olfactory bulb." (PMID 33941622, 2021). "COVID-19 patients who succumb to pneumonia and hypoxia had one hallmark feature of the profound inflammatory state that marked elevation of serum inflammatory cytokines (IL-6, IFN-γ, IL-1β, TNF-α and TGF-β) and chemokines (CCL2, CCL5, CXCL8 and CXCL10)." (PMID 34313585, 2021). "CXCL-10 was consistently found to be elevated in the serum of patients with severe COVID-19." (PMID 34745109, 2021). "CXCL10 is involved in the regulation of inflammatory and immune responses and may be a potential candidate target for treating COVID-19 related lung pathology." (PMID 34582497, 2021). "Indeed, elevated levels of CCL2, CXCL10, IL-6 and TNFα have been identified in severe COVID-19 patients compared to patients with a mild form of the disease." (PMID 34452468, 2021).
COVID-19 (continued). "Increased CXCL-10 production early in the response by males may thus be another contributing factor for the increased progression to severe COVID-19." (PMID 34745109, 2021). "Elevated production of inflammatory mediators at day 7 postinfection, a late time point, indicates that a profound immune response resulted from infection and aligns with increased levels of inflammatory mediators, including IL-1β, IFN-γ, TNF-α, and CXCL10, detected in COVID-19 patients." (PMID 33879586, 2021). "Therefore, at the time of enrolment different COVID-19 outcome groups were identifiable based on distinct patterns of inflammatory mediators; IL-6, CXCL10, and GM-CSF were key determinants of cluster assignment." (PMID 33692097, 2021). "Corticosteroids that showed beneficial effects in the most severe forms of COVID-19 may act upstream from CXCL10 through inhibition of the T cells." (PMID 34582497, 2021). "Collectively, these preliminary data suggest that the CXCL10/CXCR3 axis may participate in CD16Int neutrophil recruitment into the lungs of patients with COVID-19." (PMID 33986193, 2021). "Moreover, CXCL10 is considered a key immune event contributing to the cytokine storm observed in COVID-19 patients and a potential predictive factor of clinical outcome." (PMID 34205098, 2021). "We additionally found 4 potential targets (CCL20, CSF3, CXCL1, CXCL10) with 6 existing drugs that could be repurposed for the treatment of COVID-19." (PMID 34582497, 2021). "On the other hand, CXCL10 is also considered a crucial chemokine in COVID-19." (PMID 34224085, 2021). "Furthermore, we examined mRNA expression of cytokines (IL-6, TNF-α, and CXCL10) which are known to be upregulated in COVID-19 patients." (PMID 34815389, 2021). "Besides the cytokines, several other small chemical molecules or chemokines such as CCL2 (MCP1), CCL3 (MIP1α), CXCL10 (IP-10) have been reported to be higher in the serum of severely ill patients with COVID-19." (PMID 34066983, 2021). "Moreover, IP-10 (CXCL10) and MCP-1 have been proposed as biomarkers related to the risk of death in COVID-19 and severity." (PMID 34016150, 2021). "Interestingly, increased levels of CXCL10 were found in plasma samples of patients with COVID-19 who died." (PMID 34582497, 2021). "The slower secretion of IFN-α along with increased secretion of CXCL-10 may be responsible for worse COVID-19 outcomes in males." (PMID 34745109, 2021). "We also found that CXCL10 protein level was increased in CSF of COVID-19 patients." (PMID 34108016, 2021). "We performed a cluster analysis to investigate whether a specific molecular signature involving CXCL10 exists and plays a role in COVID-19." (PMID 34663207, 2021). "Higher plasma GM-CSF and CXCL10 were reported in COVID-19 patients and could represent the dysregulated immune response in COVID-19 patients driving the longer duration of mechanical ventilation in severe pneumonia." (PMID 33272291, 2020). "Plasma concentrations of CXCL10 were recently reported to predict disease progression in COVID-19." (PMID 33272291, 2020). "Indeed, patients with COVID-19 who displayed measurably higher levels of IP-10 (CXCL10), IL-10, and IL-6 when first admitted to hospital went on to become more severely ill." (PMID 33363221, 2020). "The “cytokine storm” concept is derived from the observation that COVID-19 patients requiring intensive care unit admission presented elevated circulating concentrations of CXCL10, CCL2, and TNFα as compared to those in which the infection was mild or moderate." (PMID 32983172, 2020). "Severe lung and systemic inflammation is believed to result from cytokine dysregulation; in patients with SARS elevated levels of cytokines such as TNF, CXCL10, IL-6, and IL-8 likely contributed to the poor outcome, strikingly similar to cytokine storm reported in severe COVID-19 patients." (PMID 33133083, 2020). "Studies have demonstrated elevated levels of CXCL10 in COVID-19 patients than healthy controls." (PMID 33569053, 2020).
COVID-19 (continued). "COVID-19 patients had higher plasma CXCL-10 and CCL5 and marginally higher GM-CSF." (PMID 33272291, 2020). "Therefore, VISTA intersects with the CXCL10 induction pathway which is of relevance to COVID-19 immunopathology." (PMID 33643285, 2020). "The results suggest that specific chemokines (such as CXCL8 and CXCL10) may play an important role in the development of COVID-19 related symptoms." (PMID 33132913, 2020). "First, CXCL10 may represent the dysregulated immune response that drives the duration of MV in COVID-19 ARDS patients." (PMID 33138839, 2020). "In addition to these clinical trials, it would be of significance to test the efficacy of CXCR3 antagonists in COVID-19 patients, considering that systemic CXCL10 levels are positively correlated with the severity of the disease." (PMID 33613280, 2020). "Corticosteroids that showed beneficial effects in the most severe forms of COVID-19 may act upstream from CXCL10 through inhibition of the Th1 pathway." (PMID 33138839, 2020). "However, Patients infected with SARS-CoV-2 who have the TNF-α gene variant (rs1800629) are protected from developing COVID-19 moderate and severe outcomes, as well as from presenting low concentrations of some pro-inflammatory cytokines and chemokines (IL-6, CCL2, and CXCL-10)." (PMID 40881695, 2025). "CXCL9 and CXCL10 are chemokines that have been widely implicated in pulmonary pathology, chronic obstructive pulmonary disease (COPD), other interstitial lung diseases (ILD), as well as pulmonary tuberculosis (TB) and also viral pneumonias, linked to COVID-19-associated ARDS." (PMID 41425601, 2025). "That patients with MASLD might have different immune responses was shown in COVID-19, where several cytokines and chemokines were linked with uncontrolled inflammation and development of severe/critical disease (such as IL-6, IL-8, IL-10, TGF-β1 and CXCL10)." (PMID 40076848, 2025). "Current research indicates that COVID-19 patients with coexisting MAFLD exhibit a distinct cytokine profile, characterized by elevated levels of interleukin (IL)-6, IL-8, IL-10, and C-X-C motif chemokine ligand 10 (CXCL10), all of which are implicated in a more severe clinical presentation." (PMID 38257811, 2024). "Notably, certain gut bacteria that were depleted in COVID-19 patients, including Bifidobacterium adolescentis, Eubacterium rectale, and Faecalibacterium prausnitzii, negatively correlated with key inflammatory cytokines like CXCL10 and IL-10." (PMID 39518964, 2024). "As clinical manifestations in the cases of both COVID-19 and PRAD may metastasize and localize in other organs and systems, we carried out a functional assessment of TMPRSS2 and CXCL10 to identify what additional genes and their protein products are related to COVID-19 and PRAD prognosis." (PMID 36239108, 2022). "Thus, modulation of CXCL10 through short-course CSA treatment may be a promising therapeutic approach to prevent progression to COVID-19 related ARDS." (PMID 35536669, 2022). "Furthermore, it has been proposed that CXCL10 may mediate the aberrant immune response that controls the duration of mechanical ventilation in patients with COVID-19 with acute respiratory distress syndrome (ARDS)." (PMID 35536669, 2022). "TGF-β might also participate in the mechanisms of ECM remodeling underlying post-COVID-19 sequelae, as it was revealed by Colarusso and others (2021) who found higher TGF-β, CXCL10, and IL-1α plasma levels in post-COVID-19 patients who exhibited ground-glass opacities in the chest CT scan." (PMID 35647937, 2022). "Therefore, CXCL10 may also be considered a prognostic and potential therapeutic marker for COVID-19 progression." (PMID 35464491, 2022). "The association between IFN-α, IL-6, and CXCL10 may reflect the systemic immune response against SARS-CoV-2 invasion into pulmonary circulation, which might be an early predictor of respiratory failure due to COVID-19." (PMID 35237279, 2022).
COVID-19 (continued). "Therefore, we cannot exclude the possibility that IFN-γ may contribute to the production of both CXCL10 and FasL during COVID-19." (PMID 36030261, 2022). "A clinical trial was recently completed using measurement of CXCL10 in a Clinical Decision Support Protocol in COVID-19 patients (NCT04389645) that positively correlated CXCL10 levels with mortality suggesting that targeting CXCL10 signaling may also be beneficial in managing disease severity." (PMID 34935438, 2022). "These miRNAs target several pro-inflammatory cytokine and chemokine genes (e.g., TNF, CCL2, CXCL9, CXCL10, IL10, VEGFA) as well as cytokine and chemokine receptors and transduction factors (IL1R1, IL2RA, IFNAR2), reported as upregulated and associated with mortality in COVID-19 patients." (PMID 36032130, 2022). "For example, vitamin D could reduce ARDS (acute respiratory distress syndrome) in the context of COVID-19 by suppressing the expression of target genes, such as IL18, CXCL9 and CXCL10, that mediate the cytokine storm associated with the severe form of the disease." (PMID 35055093, 2022). "Indeed, increased expression of these cytokines have been reported in animal models and humans with ssRNA infection; for example, mice infected with SARS-CoV-2 exhibited increased IFN-γ and CXCL10 expression in the lung at levels comparable to COVID-19 patients." (PMID 34991643, 2022). "Moreover, research data showed that inflammatory macrophages were shared and strikingly abundant in severe COVID-19 bronchoalveolar lavage samples and inflamed RA synovium, with an obvious arrangement of pro-inflammatory genes and interferon response genes such as CXCL10, CXCL9 and so on." (PMID 35464423, 2022). "Furthermore, IL-18, which increases in COVID-19 patients, has been described to potentiate CXCL10 expression; a chemokine reported to inhibit cell proliferation and promote the death of endothelial cells; this process being prevented by administrating a caspase inhibitor." (PMID 35066575, 2022). "Therefore, taking into account that CXCL10 is the main ligand for CXCR3 receptor presented on effector T lymphocytes, it seems that the chemokine is probably one of the key mediators causing dysregulation of immune responses in COVID-19." (PMID 35409036, 2022). "CXCL10 might represent a possible target for innovative treatment strategies of COVID-19 as well." (PMID 35743825, 2022). "Therefore, specifically blocking CXCL10 may be a promising therapeutic approach to blunt the development of more severe symptoms, hospitalizations, and death in COVID-19 patients." (PMID 34582497, 2021). "Previous studies reported that COVID-19 is frequently associated with a massive production of 14 cytokines including IFN-γ, IL-1RA (IL1RN), IL-2RA, IL-6, IL-10, IL-18, HGF, MCP-3 (CCL7), MIG (CXCL9), M-CSF (CSF1), G-CSF (CSF3), MIG-1a (CCL3), CTACK (CCL27), and IP-10 (CXCL10)." (PMID 34262555, 2021). "Besides confirming the significance of ACE2 and CXCL10 in COVID-19 development, we also realized the need of determining their role in lung cancer development to establish a connection between lung cancer and COVID-19 through these targeted genes." (PMID 33585826, 2021). "Hence, by analyzing both the ACE2 receptor and the CXCL10 chemokine in terms of expression, the nature of COVID-19 in lung cancer patients can be highlighted and understood at a comprehensive level and questions- why a certain cancer cohort is more susceptible to COVID-19 can be addressed." (PMID 33585826, 2021). "Specifically, we found that the expression of genes encoding proinflammatory cytokines (IL12B, IL15, IL6, IL12A and IL1B) and chemokines (CXCL9, CXCL11 and CXCL10) was broadly increased in COVID-19 patients and speculate that other viral infections may also induce expression of these genes." (PMID 33780352, 2021).